PPARG (peroxisome proliferator activated receptor gamma)
Diseases named in the same sentence as PPARG in open-access papers (continued):
Sharing a sentence is not in itself a finding about the gene and the disease.
tumor (continued). "In contrast, for dataset GSE85608, the highest PPARG expression was observed in an HSCC patient at the stage of T4aN2M1, which means that the development of the tumor in this patient was at its late stage with moderate influence on the regional lymph nodes and early appearance of metastasis." (PMID 34054937, 2021). "To explore whether PPARγ activation mediates the therapeutic effect of Alp on cancer cachexia, we used the PPARγ inhibitor GW9662 (10 μM, the dose selection was based on the tumor cell model) and assessed its impact on myotube atrophy in vitro." (PMID 34093209, 2021). "In addition the levels of Ki67, indicating proliferating cells, and downstream effector of PPARG, FASN, were also similar to NTS control in these tumours, with FASN expression levels correlating with PPARG." (PMID 33654198, 2021). "It has been reported that PPARγ agonists can promote tumor development by activating PPARγ, although they play no role in tumor initiation." (PMID 33995008, 2021). "A total of 78.4% of the tumor samples were positive for PPARγ in the cytoplasm, 21.6% showed no cytoplasmic staining." (PMID 33802010, 2021). "Our results support the connection between PPARG and chemosensitivity in HSCC tumor cells." (PMID 34054937, 2021). "Yet, unlike PPARα and PPARγ, PPARβ/δ, which is ubiquitously expressed in almost all tissues, displays an apparent pro-tumor activity." (PMID 33946986, 2021). "We also found that the methylation level of PPARG has a negative correlation with the expression level of PPARG, and the methylation level of PPARG in the tumor group was significantly higher than that in the normal group." (PMID 34567087, 2021). "Separately, by suppressing matrix metalloproteinases and antagonizing Smad3-dependent transcriptional activity, PPARγ also attenuates extracellular matrix (ECM) remodeling and epithelial–mesenchymal transition (EMT), which, in turn, leads to reduced tumor metastasis." (PMID 33946986, 2021). "Surprisingly data from RNA-Seq of the tumour samples identified AKT3 as a novel target of PPARG and the probable link between PPARG and the observed changes at the mitochondrial level given the known role of AKT3 in PGC1a regulation and mitochondrial biogenesis." (PMID 33654198, 2021). "PPARG is also correlated to TNM stages, tumor microenvironment, and tumor burden." (PMID 34567087, 2021). "It seems that PPARγ upregulation may promote malignant GBM development, but ligand-mediated activation of the receptor could have a tumor suppressive function." (PMID 32280134, 2020). "Among the top pathways, including 31 activated in at least four tumor types, we observed a strong impact of CTNNB1 as well as several other pathways described in the literature as influencing anti-tumor immunity such as MYC, PPARG and SHH (sonic hedgehog)." (PMID 33106165, 2020). "In this respect, PPARγ was demonstrated to be involved in BCP-dependent neuroprotection and tumor suppression functions, as well as hypolipidemic effects and vascular inflammation amelioration, anxiolytic, anti-oxidant, anti-arthritic and anti-inflammatory effects." (PMID 33114564, 2020). "We performed multidimensional analyses on PPARA, PPARG, PPARD, PPARGC1A, and PPARGC1B, including differential expression analysis in pan-cancer, immune subtype analysis, clinical analysis, tumor purity analysis, stemness correlation analysis, and drug responses." (PMID 33029111, 2020). "The ability of PPARγ activation to decrease cyclooxygenase-2 (COX-2) expression and induce apoptosis suggests that the PPARγ pathway might be a tumor suppressor in humans." (PMID 32028670, 2020). "Our study showed that HD-SB inhibited tumor growth both in vitro and in vivo, which might be related with apoptosis induction via the EGFR/PPARγ/PI3K/AKT pathway." (PMID 32265701, 2020). "Genistein treatment of OS cells increased PPARγ expression and led to tumor cell apoptosis as a nontoxic activator of PPARγ." (PMID 31866857, 2019).
tumor (continued). "Importantly, confocal microscopic analysis confirms apparent PPARγ and PTEN induction in tumor cells and infiltrating macrophages." (PMID 30842627, 2019). "A mass of studies have demonstrated that PPARγ agonists via inhibiting the expression of cyclinD1, cyclinB, cyclinE, CDK4 and CDK2 and increasing the expression of CDKN1A to prevent cell cycle from G1 to S phase to prohibit tumor cells proliferation." (PMID 29642873, 2018). "The combination of retinoid X receptor agonist (9-cis-retinoic acid) and troglitazone could induce the maximal inhibitory effects on tumor growth and apoptosis via promoting the formation of RXR/PPARγ heterodimer." (PMID 29483923, 2018). "Fourth, immunostaining revealed strong nuclear PPARG expression in both the adipogenic and non‐adipogenic components of AML‐Xn, including the mass of undifferentiated epithelioid cells which likely drive tumor growth." (PMID 28275008, 2017). "Furthermore, the luminal category of tumours frequently express the transcription factors RXRA, PPARG, FOXA1, and GATA3, which are known to have a crucial role in urothelial differentiation." (PMID 28195647, 2017). "In our current research, both caspase-1 inhibitors do not display significant inhibitory effects on TAM’s cell viability or growth, but leads to the disruption of PPARγ/MCAD activity and repolarization/reprogramming of TAMs, eventually suppressing the tumor growth." (PMID 28974683, 2017). "We did not observe a significant decrease in B16F10 tumor cell growth at concentrations up to 1 μm, well above the binding affinity for rosiglitazone for PPARγ (EC50 = 23 nM)." (PMID 29228682, 2017). "Consequently, we show that PPARG inhibition significantly and specifically halts the in vitro growth of both sporadic and TSC‐related AML cells and strongly limits their tumor‐initiation capacity." (PMID 28275008, 2017). "Troglitazone and pioglitazone as well as sulindac sulfide, a nonsteroidal anti-inflammatory drug known to activate PPARγ, significantly reduce primary tumor formation by A549 cells in a xenograft mouse model." (PMID 28316613, 2017). "Transcriptional profiling classified the Ta tumours as luminal (high expression of luminal markers such as GATA3, PPARG, FOXA1 and XBP1 as well as differentiation markers such as UPK1A and KRT20) as well as non-aggressive (high expression of SKAP2, FABP4, MBNL2 and ID1)." (PMID 28916750, 2017). "Similarly, in primary TAMs derived from MMTV-PyMT mouse tumor tissues, the caspase-1 inhibitor YVAD inhibited PPARγ cleavage." (PMID 28974683, 2017). "Consistently, we have demonstrated that C. sinensis exposure could remarkably induce the expression of PPARγ, which was inhibited by DEN application, indicating that C. sinensis is a potent anti-tumor herbal medicine." (PMID 27531890, 2016). "These evidences suggest that PPARγ exerts anti-tumor effects, although a lack of correlation or pro-tumor effects have also been reported." (PMID 27692066, 2016). "It is possible that the PPARγ deletion in other hematopoietic cells outside of the myeloid lineage exerted opposite albeit minor effect on tumor growth in the Tie2-g-KO mice, which was absent in the Lyz-g-KO mice." (PMID 27692066, 2016). "Furthermore, the inhibitory effects on tumour growth under treatment with PD0325901 together with rosiglitazone (RSG), an agonist of PPARγ, were better than with PD0325901 alone." (PMID 27769068, 2016). "Among the 34 samples, an absence of PPARγ expression in the tumor was demonstrated in 5 MLS patients." (PMID 27401457, 2016). "In human trials, no general correlation of the protective effect of PPARγ expression against tumor progression and chemopreventive effects of TZDs was obvious." (PMID 25866814, 2015). "PPARγ expression in well-differentiated lung adenocarcinoma was higher than in poorly differentiated tumors, suggesting that it promotes tumor formation but is not a marker for aggressive growth." (PMID 25866814, 2015).
tumor (continued). "Current data do not suggest a correlation of clinical efficacy and high PPARγ expression according to mRNA and protein expression in tumor samples." (PMID 25866814, 2015). "Based on observations in our lab and previous reports, PPARγ-WT and PPARγ-MG KO mice are not prone to spontaneous tumour formation, suggesting any tumours that arose were a result of DMBA initiation." (PMID 25889730, 2015). "For instance, under the normal PPARG circumstances, TR4 may function as a tumor suppressor to repair the damaged DNA with little ability to change the stem cell population and/or EMT." (PMID 25859557, 2015). "Furthermore, when PPARγ was depleted from ATC cells, in vitro proliferation and invasive capacity were inhibited and tumor growth was inhibited in two in vivo murine cancer models (an orthotopic thyroid model and a flank xenograft model)." (PMID 24645981, 2014). "We hypothesized and confirmed in vitro that tumor cell sensitivity to TNF-α and the subsequent NT5E expression was PPARγ-dependent." (PMID 24133572, 2013). "Importantly, in nude mice inoculated with HCC Huh7 cells, we demonstrated a synergistic inhibitory effect of the PPARγ agonist rosiglitazone and the AKT inhibitor triciribine on tumor growth." (PMID 24023668, 2013). "On the other hand, several lines of evidence have suggested that the inhibitory effect of TZDs on tumor proliferation is independent of PPARγ expression." (PMID 22808264, 2012). "In PPARγ (−/−) and PPARγ (+/+), mouse embryonic stem cells inhibition of tumor growth by two TZDs, troglitazone and ciglitazone, was independent of PPARγ activity." (PMID 23213321, 2012). "The effective anticancer properties and the underlying molecular mechanisms of these drugs in vivo remain unclear because the primary target of TZD is PPARγ, which is upregulated in HCC and seems to provide tumor-promoting responses." (PMID 23028383, 2012). "The apoptosis-inducing effects of 15d-PGJ2 through PPARγ-independent pathways, in non-resistant tumor cells, have been well reported in many studies using different assays such as caspase, annexin V staining and mitochondrial activity assays." (PMID 21957481, 2011). "Primary tumor volume was similar in PPARγflox/flox mice in the presence or absence of pioglitazone, as well as in PPARγ-Macneg mice on control chow; PPARγ-Macneg mice receiving pioglitazone exhibited a modest decrease in primary tumor size." (PMID 22145026, 2011). "Furthermore, five of the top ten NR genes that were shown to differ significantly between tumor and normal tissue were common to both datasets (i.e., AR, MR, NGFIB3, PPARγ, and RXRγ)." (PMID 21179495, 2010). "The PPARγ transcript, as assessed by quantitative real-time reverse transcriptase PCR, did not significantly differ in tumours from control or RGZ-treated (4 weeks) mice." (PMID 20068562, 2010). "In a multivariate Cox regression model, using primary tumor stage (pTis-pT3 versus pT4) and PPARG expression (negative versus positive) as covariates, neither PPARG immunoreactivity nor primary tumor stage remained significant (data not shown)." (PMID 19639032, 2009). "The increased tumor burden eventually led to shorter survival.Interestingly, hemizygosity of PPARγ inthe MMTV-PyV background did not change the time course of tumor development." (PMID 18784849, 2008). "This appears to be independent of how PPARγ isactivated or reduced, whereas in genetic tumor models (un-shaded rows), the receptor exhibited all possible different effects." (PMID 18784849, 2008). "Indeed,some of the most prominent tumor-promoting mediators of macrophages—TNFα, MMP9, iNOS—are known to be repressed by PPARγ ligation." (PMID 18615187, 2008). "The protective effect of PPARγ positivity was not changed in multivariate modeling with tamoxifen, radiation therapy, tumor size, estrogen receptor status and margin status." (PMID 18237383, 2008).
tumor (continued). "When MK866 was combined with ciglitazone andthe RXR agonist, 13-cis-retinoic acid, there was a superadditive growthinhibitory effect compared to each drug alone.These results suggest that the induction of PPARγ and RXRα by MK866 sensitizes tumor cells to apoptosisby PPARγ ligands or retinoids." (PMID 18615184, 2008). "Synthetic (PPARγ) agonists such as the thiazolidinedione (TZD) class of anti-diabetic drugs can decrease COX-2 levels, inhibit growth of non-small-cell lung cancer (NSCLC) cells in vitro, and block tumor progression in xenograft models." (PMID 18769553, 2008). "In the current review, wewill discuss this janus-faced role of PPARγ and its ligands in cancer with amajor focus on its crosstalk with the ERK signaling cascade, which is a centralsignaling pathway deregulated in a majority of tumor types in humans." (PMID 18596912, 2008). "Therefore, a close examination ofindividual tumor types and their response to PPAR stimulation will be criticalfor successful cancer therapy targeting PPARs, particularly PPARγ." (PMID 18615184, 2008). "The message was found in three ofsix tumor tissues while the corresponding normal tissues do not express PPARγ." (PMID 18784849, 2008). "Another group also found that the PPARγ immunostainingin well-, moderately-, or poorly-differentiated gastric adenocarcinomas iscomparable to that in noncancerous tissue adjacent to the tumor." (PMID 18784849, 2008). "In DRO cells derived from ATC tumor, they demonstrated that upregulationof p21 by RS5444 is PPARγ dependent,and might be the major mechanism by which RS5444 inhibits DRO cellproliferation." (PMID 18725985, 2008). "The reason for the different effects of PPAR ligands, that is, decrease ofcell proliferation in some tumor cells inducing PPARγ, or inductionof apoptosis in others inducing PPARα, is not yet clear." (PMID 17389773, 2007). "While the PPARγ role in tumour growth has not been clearly defined, the involvement of the altered polyamine metabolism in colorectal carcinogenesis has been established." (PMID 16854216, 2006). "Tumour stroma or endothelial cells lining the blood vessels were negative for PPARγ immunoreactivity." (PMID 15583697, 2005). "When statistical analysis was performed between PPARγ-positive and -negative tumours, we observed that 86% (six of seven) of FTCs with distant metastasis were PPARγ negative (P=0.03)." (PMID 15238980, 2004). "Previous studies have shown that FTCs harbouring the fusion gene, hence strongly reactive with a PPARγ antibody, are somewhat smaller in size, more overtly invasive, and occur at a younger age than tumours without the rearrangement." (PMID 15238980, 2004). "By real-time RT–PCR, we observed that tumours negative for the PAX8-PPARγ rearrangement expressed lower levels of PPARγ mRNA than the NT." (PMID 15238980, 2004). "We observed that tumours negative for the rearrangement expressed lower levels of PPARγ mRNA than NT." (PMID 15238980, 2004). "Most (75%) of the widely invasive FTCs were PPARγ negative, whereas only 38% of minimally invasive tumours did not shown PPARγ staining." (PMID 15238980, 2004). "We investigated the HPA immunohistochemistry and DepMap CRISPR screenings to confirm the tumor-intrinsic essentiality of PLK1 and AURKA, while utilizing the TISCH single-cell dataset to validate the microenvironmental specificity of CTLA4 (T-cells) and PPARG (CAFs/Macrophages)." (PMID 41596281, 2026). "The anti-tumor and pro-tumor effects of I2 were independent of androgens and PPARG." (PMID 40869121, 2025). "The 15-deoxy-Δ 12,14 prostaglandin J 2 (15-d-PGJ-2) is a PGD2 metabolite and a natural ligand for peroxisome proliferator-activated receptor-γ (PPARγ) which is activated by dependent or non-dependent signaling and exert anti-tumor, anti-inflammatory, and anti-angiogenic actions." (PMID 38704736, 2024).
tumor (continued). "In a mouse orthotopic transplantation tumor model, after PPARγ was inhibited, the immune cell population increased; these cells included both dendritic cells and CD8+ T cells and were recruited through ferroptosis and disulfidptosis, leading to the inhibition of tumor development in OSCC." (PMID 38786003, 2024). "Notably, KRAS mutant cases with high POM121 protein positivity had more PPARγ protein localized to the peri-nuclear and cytoplasmic regions of the tumor cells compared with KRAS wt cases, who showed nuclear positivity of PPARγ (n = 208, *p < 0.05, Fisher Exact test)." (PMID 38177114, 2024). "Similarly, although PPARγ has been extensively studied in the metabolic regulation of tumor cells, due to its complex regulatory network does not allow conclusions to be reduced to simple cancer promotion or suppression." (PMID 37251321, 2023). "By means of in vitro and in vivo studies, these authors could show that, in PCa cells, PPARG overexpression induces AKT3 expression leading to increased mitochondrial biogenesis and ATP production, finally fueling tumor cell epithelial-to-mesenchymal transition (EMT) and metastatic behavior." (PMID 36831534, 2023). "However, significant expression variation of PPARG exists in chemotherapy-sensitive patients, which may be influenced by multiple factors, including the TNM (tumor, node, and metastasis) stage, a predictor of chemosensitivity." (PMID 37791141, 2023). "Finally, we found that vascularization significantly increased in the MCF10ADCIS.com tumor when coinjected with control pericytes compared to PPARγ-overexpressing pericytes or no pericytes." (PMID 37816052, 2023). "However, PPARδ expression was unexpectedly found to be significantly upregulated in B cells from draining lymph nodes (dLNs) of tumor-bearing mice, while PPARγ expression was undetectable in these B cells (data not shown)." (PMID 37291146, 2023). "Notably, mice implanted with the USP22-overexpressing MHCC-97L cells formed larger tumors compared to those implanted with the control MHCC-97L cells; however, MHCC-97L cells with simultaneous USP22 overexpression and PPARγ, ACC or ACLY knockdown showed lower tumor growth rates." (PMID 35449157, 2022). "Moreover, PPARγ and SIRT1 were substantially expressed in ESCC tissues, but high PPARγ expression was correlated with tumor grading but not with poor prognosis." (PMID 36142861, 2022). "Collectively, these results suggested that PPARγ has a critical function in the terminal differentiation of MMP9+ TAMs in HCC, which could promote HCC progression through inducing HCC cells migration, invasion, and tumor angiogenesis." (PMID 35933472, 2022). "And they argue that the reason for the high expression of PPARγ protein in NSCLC may be the lack of PPARγ endogenous ligands in tumor tissue." (PMID 35911149, 2022). "In this study we identify a previously unknown role for PPARG in up-regulating AKT3, which promotes PGC1α localisation to the nucleus and consequently increases mitochondrial mass and function, increasing ATP levels, tumour growth and metastasis." (PMID 33654198, 2021). "For inoperable, metastatic, and recurrent ML tumours that do not respond to conventional treatments, PPARγ agonists may offer long term suppression of disease activity." (PMID 33669307, 2021). "Based on in vitro findings, PPARγ ligands were tested in murine breast cancer xenograft models where they proved to be effective in counteracting tumor growth, without inducing toxic effects either in combined PPARγ/RXR treatments or alone compared to controls." (PMID 34067944, 2021). "The PPARG CRISPR construct used to generate the clones also contained the gene for red fluorescent protein (RFP), thus IHC for RFP could be used to determine if the tumours that had developed had derived from cells still expressing this construct." (PMID 33654198, 2021).